MIF (macrophage migration inhibitory factor)
Diseases named in the same sentence as MIF in open-access papers (continued):
Sharing a sentence is not in itself a finding about the gene and the disease.
tumor (continued). "Besides hallmark signatures, we observed differential expression of MIF in Prot3, which could potentially be related to IFN‐gamma and tumor‐associated macrophage activation, leading to an immune‐suppressive environment." (PMID 38650175, 2024). "CXCR4 binds macrophage migration inhibitory factor (MIF), a factor implicated in the control of innate immunity, as well as CXCL12, a molecule well-known for its function in immunological surveillance, inflammatory response, tissue homeostasis, and tumor development and metastasis." (PMID 37190141, 2023). "Interestingly, in an analysis of intercellular communication, this study found that the communication strength between malignant and immune cells in the MIF pathway was significantly greater in the setting of HCC with higher levels of oxidative stress than in the setting of non-tumor hepatocytes." (PMID 37842089, 2023). "In vivo, different immune cells such as macrophages and neutrophils can contribute to the generation of reactive oxygen species (ROS) and pro-inflammatory mediators, oxidizing conditions that may also occur within the tumor microenvironment, wherein MIF could be converted to oxMIF." (PMID 36672343, 2023). "Therefore, the B16 tumour model and other cold tumours with similar T-cell desertification issues are not likely to naturally respond to ICT and would benefit from combinatorial approaches that block the MIF/CD74 axis to unleash DCs-dependent priming of anti-tumour CD8 + T cells." (PMID 37454231, 2023). "Moreover, scRNA-seq analysis revealed that fibroblast and ductal cells might affect malignant tumor cells via MIF-(CD74+CD44) and SPP1-CD44 axis." (PMID 38095640, 2023). "It has been speculated that intracellular MIF in the breast cells has a protective function, whereas extracellular MIF, whether it is tumour-associated macrophage (TAM)-derived or produced by carcinoma cells upon stroma/tumour interactions, is pathogenic." (PMID 35012533, 2022). "However, again a word of caution is needed, because MIF (and maybe D-DT) are also important in promoting tumor growth and nurturing a local tumor microenvironment through chronic inflammation." (PMID 35091838, 2022). "Both TA-MSCs and TA-MSCs-EVs can up-regulate the expression levels of angiogenic cytokines in tumor cells, MIF may play an important role in the process because it also upregulates angiogenic cytokines by binding to CD74 receptors and activating related signaling pathways." (PMID 35842634, 2022). "Besides, we could not show the significant association between CD74 and MIF expressions in tumor tissues, including tumor-infiltrating immune cells and sCD74 and MIF levels in paired sera, respectively." (PMID 35121729, 2022). "Therefore, tumor cells aberrantly elevate MIF expression via Hsp90-mediated protein stabilization." (PMID 33542244, 2021). "In sum, MIF/CD74 co-expression might be the major predictor for tumor growth in CRC." (PMID 33542244, 2021). "Macrophage migration inhibitory factor (MIF) was originally found to act as a proinflammatory cytokine in immune and inflammatory responses, to mediate the regulation of macrophage function to counteract the anti-inflammatory activity of glucocorticoids, and to have tumor-promoting properties." (PMID 34109216, 2021). "As tumor progression was successfully inhibited through administration of rSmeg-hMIF-hIL-7, a cell-mediated immune response in addition to elevated humoral anti-MIF IgG may work together to inhibit tumor growth." (PMID 34389619, 2021). "However, the role of MIF’s nuclease activity in DNA replication and tumor growth remains completely unknown." (PMID 34012010, 2021). "Therefore, MIF supports tumor growth through significantly enhancing angiogenesis." (PMID 33776775, 2021).
tumor (continued). "Indeed, several pro-proliferation proteins were uniquely identified in CM2D such as PICALM, which positively regulate cell proliferation and GPC6, MAPK1, ILK and MIF, all involved in cell proliferation, migration and invasion, including that of tumor cells, cardiomyocytes and endothelial cells." (PMID 34884877, 2021). "Also, MIF molecules may participate in accumulation of macrophages related to PCa and affect on tumor maintenance." (PMID 34157052, 2021). "All things combined, MIF influences B cell activation pathways at multiple stages of development and maturation but whether these activation phenotypes occur during tumorigenesis and extrapolate to tumor immunity is largely unexplored." (PMID 33324425, 2020). "Additionally, studies that looked at DC MHC-II expression found that MIF promotes downregulation of MHC-II, which further suggests that MIF may also impair tumor antigen presentation of DCs to CD4+ T cells." (PMID 33324425, 2020). "Combined, these findings indicate that loss or inhibition of MIF in solid tumor settings very efficiently re-polarizes intratumoral TAMs from an immunosuppressive/angiogenic pro-tumor phenotype to an immunostimulatory/non-angiogenic anti-tumor phenotype." (PMID 33324425, 2020). "A possible explanation for this could be the lack of association of MIF and TNFα which play a role in the site of tumor where the inflammatory process is exacerbated; therefore, more studies are necessary for the determination of these cytokines in situ." (PMID 31978276, 2020). "Similarly, MIF promotes tumor cell invasiveness, inducing macrophage secretion of MMP." (PMID 32354198, 2020). "The distribution of MIF may reflect its role in tumor development." (PMID 31360118, 2019). "In addition, MIF also acts on tumor cells to facilitate cell proliferation and cell survival." (PMID 31293831, 2019). "On the other hand, overexpression of Vegf in HapT1 cells upon stimulation with MaMIF and presence of more number of blood vessels in HapT1 tumors suggest a possible mechanism through which circulating MIF might indirectly enhance HapT1 tumor growth by promoting angiogenesis in vivo." (PMID 31664114, 2019). "Furthermore, we analyzed the influence of MIF in the modeling of the tumor microenvironment." (PMID 31360118, 2019). "Therefore, our observations suggest that ICD could be induced by inhibiting MIF, which would represent another means to increase tumor immunogenicity beyond the previously identified therapeutic approaches." (PMID 29864117, 2018). "Finally, cytoplasmic MIF was clearly observed in all H2052/484 tumor cells." (PMID 29949929, 2018). "In addition to its key role in diverse inflammatory processes, MIF may be secreted by tumors, and its potential as a (tumor) biomarker has also been investigated." (PMID 30475854, 2018). "Since tumor B3GALNT2 decreased acetoacetate levels we speculated that B3GALNT2-modulated effects on macrophage recruitment are associated with MIF activities." (PMID 29618368, 2018). "Thus, CD74 appeared to be primarily expressed in malignant mesothelial cells, indicating that such tumor cells may be prone to stimulation with MIF." (PMID 26883190, 2016). "In the context of tumor biology, MIF has been shown to induce the infiltration of several cell types into tumors, including myeloid derived suppressor cells (MDSC), neutrophils, and mast cells, as well as to affect the polarization of tumor associated macrophages." (PMID 26741693, 2016). "Finally, we found increased MIF secretion in tumor bearing mice following exposure to radiation." (PMID 26741693, 2016). "Interestingly, MIF expression was positively related to the tumor size of live metastases." (PMID 26087187, 2015).
tumor (continued). "In addition to auto- and paracrine effects on cancer cells, MIF could contribute to shape the tumor microenvironment leading to immunomodulation and angiogenesis." (PMID 24939415, 2014). "Additionally, MIF and cyclin D1 expression positively correlated with tumor size." (PMID 25015194, 2014). "Furthermore, MIF is related with incidence of tumor metastasis in patients." (PMID 24167613, 2013). "Importantly, MIF and CXCR4 expression levels in tumor cells and in TILs were positively associated." (PMID 23497377, 2013). "Our results suggest that MIF could be expressed in the cytoplasm of tumor cells and TILs." (PMID 23497377, 2013). "Furthermore, we determined that, with the exception of classical prognostic factors such as gender and WHO grade, the expression of MIF or CXCR4 in tumor cells and the MIF expression in TILs were independent predictors of DFS and OS according to the multivariate Cox model analysis." (PMID 23497377, 2013). "However, whether MIF deletion in tumors makes them prone to hypoxia and affects tumor vasculature in vivo remains to be thoroughly investigated." (PMID 22973314, 2012). "MIF may indirectly facilitate tumor growth via promotion of angiogenic response." (PMID 21283538, 2011). "The mechanism by which MIF may facilitate invasion of tumor cells is currently unknown." (PMID 17650334, 2007). "Additionally, we have recently reported both in vitro and in vivo evidence that MIF promotes bladder muscle cell death which could facilitate tumor cell invasion." (PMID 17650334, 2007). "In contrast to the notion of MIF as tumor promoter, two reports have indicated that aberrantly low levels of MIF in human tumors could also correlate with poor clinical prognosis and that subcellular compartimentalization of MIF may likewise be relevant." (PMID 17640378, 2007). "Pan-cancer analyses have further identified macrophage migration inhibitory factor (MIF), which serves as a marker of M0 macrophages, as a strong correlate of tumor-related immunosuppression." (PMID 41514936, 2026). "Cell communication analysis revealed extensive interactions between TRMs and other cell types, including CXCL/MIF and notably upregulated SPP1 signalling in tumour tissues." (PMID 42210511, 2026). "By contrast, the interaction between bone metastatic PC tumor cells and SPP1+ TAMs was mediated by the macrophage migration inhibitory factor (MIF) signaling pathway." (PMID 41362730, 2026). "Compared to single-cell data, the proportion of MIF and HMGCR expression in cholesterol-synthesizing tumor cells were lower in spatial transcriptomics." (PMID 41355948, 2026). "It was demonstrated MIF 30 and cholesterol biosynthesis 31, as well as HMGCR 32, 33—a rate-limiting enzyme in cholesterol synthesis—are upregulated in ESCC tumor cells." (PMID 41355948, 2026). "Recombinant MIF alone similarly suppressed NDRG1 and enhanced survival, highlighting its dual role as both a mediator of WISP1 activity and an independent tumor-promoting factor." (PMID 41597235, 2026). "Differential gene expression confirmed elevated levels of MIF, CD74, CD44, and SPP1 in tumor tissues, while pathway enrichment analyses highlighted cytokine signaling, antigen presentation, and chemokine-regulated immune modulation as key biological processes." (PMID 41683916, 2026). "Responders exhibit a dominant signature characterized by IL1B, MIF, CXCL5, and HMGB1—indicating an inflamed, neutrophil-rich tumor microenvironment (TME) that is primed for antitumor immunity." (PMID 40723289, 2025). "In HPV-coinfected malignancies, such as cervical cancer, KSHV amplifies pathogenesis by up-regulating MIF and CXCR2 in tumor cells, creating feedforward loops that recruit and activate TAMs, despite down-regulation of HPV E6/E7 oncoproteins." (PMID 41355895, 2025). "These tumor subtypes cooperatively drive CD8+ T cell exhaustion through the MDK–(ITGA4+ITGB1), MIF–(CD74+CXCR4), and TGF-β signaling pathways." (PMID 40948762, 2025).
tumor (continued). "Conversely, Scissor- tumor cells displayed a pro-angiogenic and immune-activating phenotype by eliciting NOTCH/VEGF signaling and NECTIN/MIF/IL1 signaling, respectively." (PMID 40098972, 2025). "This process is functionally tied to PCSK9, which influences tumour cell EMT and the PI3K/AKT signalling cascade by suppressing lactate levels, histone lactylation and macrophage migration inhibitory factor (MIF) activity." (PMID 41190507, 2025). "Mechanistically, MIF can enhance epithelial-to-mesenchymal transition (EMT), regulate tumor suppressor genes, and create hypoxic and inflammatory tumor microenvironments that promote tumor progression and immune evasion." (PMID 41472252, 2025). "Another study found a positive correlation between high MIF expression in OSCC and second primary tumor recurrence." (PMID 41159021, 2025). "Tumor area activated various proliferation and metastasis-related signaling pathways (MK, SPP1, SEMA3, MIF, VEGF, PERIOSTIN, and PDGF) and immunosuppression-related signaling pathway (GALECTIN)." (PMID 39670859, 2025). "We found that the signaling of VEGFA-VEGFR1, VEGFA-VEGFR2, MIF-(CD74 + CXCR4) and MIF-(CD74 + CD44) was significantly increased in the high-risk state; whereas the signaling of LGALS9-CD45, LGALS9-CD44, and IL1B-IL1R2 was decreased, which may affect the tumor cell adhesion and migration." (PMID 40563096, 2025). "At a defined tumor burden, mainly at week 6 after AOM induction, genetic ablation of epithelial MIF was induced by TAM (abbreviated by MifΔ/Δ;TP53Q/+)." (PMID 40835826, 2025). "MIF and its functional paralogue D‐dopachrome tautomerase (D‐DT or MIF‐2) have overlapping but nonidentical signaling functions and are hypothesized to generate immune suppressive tumor microenvironments characterized by T‐cell suppression and tumor‐permissive macrophage populations." (PMID 40131169, 2025). "Tumor cells followed a similar trend, increasing in CD74 MIF (β = 0.219, p = 0.005) and MIF CD44 (β = 0.190, p < 0.0001), further supporting their role as hubs of immune activation and tumor presence in advanced disease." (PMID 40364843, 2025). "Subsequently, we examined the ligand-receptor pairs of these signals, noting that ligands such as MIF, MDK, and APP are highly expressed on C0 RPS4Y1+ tumor cells and are instrumental in mediating communication with other tumor microenvironments." (PMID 40230840, 2025). "We made an interesting observation through cell-cell communication analysis: compared to other clusters of tumor epithelial cells, clusters EPI12, EPI4, and EPI5 prominently interact with macrophages via the MIF signaling pathway." (PMID 41235252, 2025). "Most notably, MIF–CD74_CD44 signaling, known to induce immune suppression and matrix metalloproteinase (MMP)-mediated tumor invasion, was markedly downregulated." (PMID 40941002, 2025). "Previous studies have shown that the MIF signaling axis shapes an immunosuppressive TIME through the ERK1/2, AMPK, and AKT pathways and enhances tumor tolerance to oxidative stress." (PMID 40740771, 2025). "The interaction between MIF and its receptor CXCR2 on MDSCs induces the migration of MDSCs toward the tumor sites." (PMID 41159021, 2025). "Numerous cytokines and chemokines such as IL-6, IL-1β, G-CSF, M-CSF, GM-CSF, macrophage migration inhibitory factor (MIF), and TGF-1 were present in the TME which attract MDSCs accumulation at tumor sites." (PMID 40141437, 2025). "The interaction that existed between MIF, its receptor CD74, and the chemokine receptor, CXCR4, is crucial in tumor biology, particularly cancer progression and metastasis." (PMID 40066443, 2025). "They influence cancer progression by modulating the MIF and TNF pathways, directly promoting tumor growth." (PMID 40136652, 2025). "Single‐cell profiling uncovered extensive communication networks centred on myeloid cell populations, with MIF and GALECTIN pathways emerging as critical mediators of tumour development and immune suppression." (PMID 40596746, 2025).
tumor (continued). "Driving lipid metabolic reprogramming and immunosuppression through MIF-(CD74+CD44)-mediated macrophage polarization, our work finds FOS as a master regulator of the malignant C0 MAFF+ tumor cell subtype in LUAD." (PMID 40936936, 2025). "Cell-cell interaction analysis demonstrated strong communication between CGR11-high tumor cells and immune components (TAMs, TECs, T cells) via ligand-receptor pairs such as CD6, CD46, MIF, VEGF, and TRAIL." (PMID 41573680, 2025). "This transdifferentiation was propelled by the macrophage migration inhibitory factor (MIF), which was secreted by tumor cells and activated the JAK/STAT3 signaling pathway." (PMID 39891284, 2025). "Based on the transcription-level CellChat data, MIF and APP tumor–immune signaling has a high probability of taking place in pRMS." (PMID 41373578, 2025). "As a downstream molecule of MIF, IL-8 is also elevated in NPC tumor tissues and poorly differentiated NPC cell lines." (PMID 41472252, 2025). "MIF was predicted to interact with CD8+ T cells through the CD74 receptor and MDK with NK cells through the SORL1 receptor, with interactions with tumor cells demonstrating the highest predicted probability." (PMID 39908652, 2025). "When treated with recombinant MIF (rMIF) at doses in the range of 0–150 ng/ml, MCF-12A and both tumor cell lines demonstrated increased proliferation, with the strongest effect observed in cells with the highest CD74 expression which are MDA-MB-231." (PMID 41159021, 2025). "Chemotactic interactions promote attraction and activation of cytotoxic cell subsets, likely promoting anti-tumor activity in the TME of R (pDC GPI → NK AMFR, pDC MIF → NK T CD74/CXCR4, and NK T CCL3L1 → CD8 + T CCR5)." (PMID 41185627, 2025). "Subsequent CellChat analysis revealed enhanced interactions between ACACA-high tumor cells and CD8+ T cells, primarily via secreted signaling pathways like the macrophage migration inhibitory factor (MIF) axis (MIF-CD74+CXCR4, MIF-(CD274+CD44))." (PMID 41169354, 2025). "MIF activates the PI3K/AKT signaling pathway, inhibits apoptosis in tumor cells, and facilitates tumor growth and metastasis." (PMID 40110199, 2025). "Tumor cells were also significantly more localized within CD74 MIF and MIF CD44 neighborhoods, reinforcing the role of these regions as hubs of immune suppression." (PMID 40364843, 2025). "Macrophages and OS cells emerged as dominant sources of multiple tumor-relevant signals, including SPP1, TNF, MIF, GALECTIN, ANNEXIN, and VEGF." (PMID 40895569, 2025). "The interaction between TANs and MIF influences TAN activities and tumor progression, structuring the immune compartment of TME." (PMID 41159021, 2025). "Blocking specific molecular axes, such as the macrophage migration inhibitory factor (MIF)/CD74 pathway, can polarize microglial cells into a pro-inflammatory state, potentially inhibiting tumor progression after radiation treatment." (PMID 39857798, 2025). "MIF-KO and CATT5 mice exhibited reduced tumor burdens compared with WT or CATT7 mice alone and in the presence of anti–PD-1." (PMID 41122966, 2025). "Our analysis identified specific signaling pathways, including MIF and SPP1 signaling in subtype 1, which were noted for their implications in tumor progression and immunosuppression." (PMID 40761262, 2025). "The tumour area activated various proliferation and metastasis‐related signalling pathways (such as MK, SEMA3, MIF, ANGPT, EGF and VEGF)." (PMID 39187937, 2024). "With increasing studies demonstrating that MIF and DDT enhance immunosuppressive and pro-tumorigenic phenotypes, these cytokines have emerged as promising antitumor targets across a variety of tumor types." (PMID 38732068, 2024). "Our study found that in HNSCC, SHMT2 suppresses anti-tumor immune responses by down-regulating CD44 expression and inhibiting T cell activation through MIF." (PMID 38625586, 2024).